CD4 (CD4 molecule)
Diseases named in the same sentence as CD4 in open-access papers (continued):
Sharing a sentence is not in itself a finding about the gene and the disease.
Opportunistic infection (continued). "Emphasis should be laid on prompt initiation, support of patients, and ART adherence, to reduce the debilitating effect of low CD4 counts and opportunistic infections that may increase chances of death and other unfavourable outcomes." (PMID 31420021, 2019). "Although the children in this study were stable on ART with high CD4+ cell count and virally suppressed at the time of the study, low nadir CD4+ cell count and/or opportunistic infections may have occurred and contributed to cardiac damage." (PMID 30289814, 2018). "However TB still remained a major presenting opportunistic infection with the majority of cases occurring at low CD4 counts." (PMID 30064368, 2018). "In the setting of HIV, cerebral lesions are usually secondary to lymphoma and opportunistic infections; however, in patients with CD4 counts above 200 cells/uL, other pathologies such as pyogenic brain abscess could gain importance." (PMID 29149022, 2017). "An analogous condition in adults, idiopathic CD4+ lymphocytopenia, was described in a prospective cohort study involving 39 patients who were diagnosed via an incidental laboratory finding or an unexplained opportunistic infection." (PMID 28770187, 2017). "Recent advances in HIV therapy have improved the quality and longevity of HIV-infected patients’ lives due to suppression of viral load, improvement of CD4 T cell counts and reduction to almost elimination of opportunistic infection in developed countries, especially United States." (PMID 28979590, 2017). "HIV attacks CD4-positive cells as its host cells in the human body, reducing the number and quality of these immune cells, leading to increased morbidity and mortality from opportunistic infections." (PMID 28702270, 2017). "The combination of low CD4/CD8 ratio and CMV seropositivity has been identified as an “immunological risk profile” and recently shown to predict severe bacterial infections and opportunistic infections after kidney transplant." (PMID 28562595, 2017). "Patients particularly at risk of secondary opportunistic infections include immune ‘non-responders’ who have low CD4 counts in spite of a suppressed VL." (PMID 28199360, 2017). "Various studies have shown that low baseline CD4 count and advance disease stage were significant predictors of treatment failure explained by the frequent occurrence of opportunistic infections that leads to disease progression subsequently increased risk of failure." (PMID 29095936, 2017). "Cryptococcosis is an opportunistic infection caused by the encapsulated yeast Cryptococcus neoformans and most remarkably manifests in HIV-infected individuals, especially in the settings of very low CD4 count." (PMID 28446137, 2017). "However, no previous study had holistically examined the impact on survival, CD4 recovery and occurrence of opportunistic infections of malnutrition at the time of starting HAART." (PMID 27688793, 2016). "However, different opportunistic infections occur at varying levels of CD4+ depletion and immune function." (PMID 27716818, 2016). "Similarly, the chances of opportunistic infection in patients having CD4 T-cell count <200 was about 3.5 times higher (OR = 3.4, 95 % CI 1.1–10.1) than in other patients." (PMID 27048153, 2016). "Lymphopenia may increase the risk of serious opportunistic infections, as seen in HIV positive patients, primary immunodeficiency, idiopathic CD4+-Lymphopenia and chronic immunosuppressive therapy." (PMID 27214202, 2016). "In patients with low CD4 counts, MTX may predispose patients further to opportunistic infections, including TB." (PMID 27366339, 2016). "Improved survival and decreased incidence of opportunistic infections go hand in hand with a suppression of the plasma viral load, an increase in peripheral CD4+ T-cell counts, as well as a reduction in the activation status of both CD4+ and CD8+ T cells." (PMID 27819062, 2016).
Opportunistic infection (continued). "Apart from CD4 T cell depletion, there are many other immunological phenomena that may impact on the ability of the host to control opportunistic infections such as C. neoformans infection." (PMID 26252005, 2015). "Utilities depend on CD4+ cell count and the occurrence of opportunistic infections." (PMID 26714188, 2015). "In multivariate analysis (adjusting for study visit, sex, age, diagnosis of depression, income per month, WHO stage, education level, baseline CD4 count and opportunistic infection), there was a 0.50 mean increase in PHS at six months compared with baseline visit (95 % CI 0.06 to 0.93)." (PMID 26216221, 2015). "Individuals initiating treatment at high CD4 counts were likely to be different in some way; for example, they may be presenting for care due to an opportunistic infection." (PMID 25779383, 2015). "However, the two groups were different with regard to baseline age distribution (P = 0.025), baseline CD4 values (P≤0.001), history of opportunistic infections (P = 0.017) and adherence characteristics to the ART (P = 0.001)." (PMID 26348618, 2015). "Pathogen-specific differences that we observed in the natural frequency and phenotype of the CD4+ response may underlie inherent immune vulnerabilities in HIV co-infection and shape the timing of opportunistic infections." (PMID 26417433, 2015). "Therefore, the direct effect of HIV viremia on the kidneys seems to contribute more to the development of albuminuria than opportunistic infections (related to CD4 count) or nephrotoxic effects of ART in use in this population." (PMID 26309226, 2015). "In the long run, CD4 testing is likely to become less frequent as a blanket diagnostic tool, but will remain important as eligibility assessment for ART and for preventive treatment of opportunistic infections." (PMID 26295802, 2015). "Previous studies had reported a variety of risk factors including alcohol and substance abuse, lower nadir CD4 counts, cardiovascular/metabolic diseases, psychiatric disorders, hepatitis C virus coinfection, host genetic factors, virus subtype, anemia, and opportunistic infections." (PMID 26295033, 2015). "Your CD4 count is high enough that you’re protected from opportunistic infections." (PMID 26263532, 2015). "Malnutrition is prevalent due to infection, decreased caloric intake, malabsorption, increased energy needs, and opportunistic infections, resulting in decreased CD4 count leading to a weakened immune system diminishing the ability to respond to therapeutic treatment." (PMID 25995722, 2015). "Additionally, decentralization of CD4+ T cell testing will allow for quicker management of opportunistic infections in ART patients." (PMID 26720601, 2015). "Chemotherapy aggravates the immunodeficient state of myeloma patients, resulting in significant reductions in CD4+ as well as specific reductions in CD4+ CD45RO+ cells as compared to untreated myeloma; this decrease is strongly associated with opportunistic infections." (PMID 24917865, 2014). "Late diagnosis and late ART initiation are strongly associated with negative health outcomes, including suboptimal CD4 increases with treatment, a high rate of opportunistic infections, and increased risk of mortality." (PMID 24901790, 2014). "Human CD4+ T cells are critical regulators of the immune system, as drastically demonstrated by HIV-infected individuals that develop susceptibility to opportunistic infections and cancer when virus-dependent depletion reduces CD4+ T cell counts below critical thresholds." (PMID 25566245, 2014). "As the CD4 T-lymphocyte is the primary target of HIV, the CD4 count is commonly used as a surrogate laboratory indicator of the degree of immunocompromise and potential risk of opportunistic infections, including CMV retinitis." (PMID 25336901, 2014).
Opportunistic infection (continued). "When the level of CD4+T-cells drops from around 1000 cells per mm3 (the normal level for a healthy individual) to about 200 cells per mm3, the cell-mediated immunity is lost and the body becomes progressively more vulnerable to opportunistic infections." (PMID 24963975, 2014). "Similarly, mortality and new opportunistic infection (OI) rates were low and similar between groups with sub-optimal and optimal CD4 recovery, respectively in a North American cohort study." (PMID 24594114, 2014). "The role of CD4+T-cells in regulating and amplifying the immune response is vital, and a decline in their number results in deficits in humoral and cell-mediated immunity, opening an opportunity for opportunistic infections." (PMID 24963975, 2014). "The improvements in CD4 counts were not more closely associated with improvements in opportunistic infection, surprising finding given results from other studies comparing CD4 counts with the incidence of such infections." (PMID 24977038, 2014). "Since urban participants were significantly more likely to have CD4 counts <200 cells/mm3 up to 12 months on HAART, it may be that they are immune-compromised and more susceptible to opportunistic infections, such as TB, and early mortality." (PMID 25280741, 2014). "Effective HAART results in increased CD4 counts and reduced risk of opportunistic infections, but HAART does not fully restore immune function." (PMID 24499779, 2014). "However, these children still had the lowest absolute CD4 cell counts, and a significantly higher proportion experienced an opportunistic infection." (PMID 24994004, 2014). "The authors concluded that earlier HAART initiation, before the development of a low CD4 cell count and opportunistic infection, may reduce the incidence of adverse effects." (PMID 25368714, 2014). "Although other accompanying opportunistic infections may also have explained the reduced CD4 count among our HIV-HBV-coinfected patients, this confounding factor was outside the scope of present study." (PMID 23691352, 2013). "Another challenge is assessing the time between poor adherence and death, and that several other events may happen during that time period, such as increased viral load, lowered CD4 counts, changing drug regimes and opportunistic infections." (PMID 24060199, 2013). "The recovery of cellular immunity with HAART may partially reverse susceptibility to opportunistic infections when it achieves sustained undetectable levels of HIV-RNA and CD4+ levels above 500 cells/mm3 over a long period of time." (PMID 23510319, 2013). "Importantly, CD4 cell counts also improved such that 89% of our patients had ≥200 cells/μL by the end of 2011, above the generally recognized threshold for opportunistic infections." (PMID 23437255, 2013). "Our study clearly shows that comprehensive baseline treatment preparation efforts needs to intensify adherence counseling, address anemia, male health seeking behavior, active case detection for opportunistic infections, affordable viral load testing, and regular CD4 cell count testing." (PMID 23452915, 2013). "The flare of opportunistic infections may be provoked by the transient increase of CD40L-expressing CD4+ T cells suppressing type I interferon production." (PMID 22470494, 2012). "On the other hand, severe lymphocytopenia and CD4+ T lymphocytopenia like that found in these six patients and associated with clinical immunodeficiency with opportunistic infections has not been reported in association with chronic herpes virus infections." (PMID 24893304, 2012). "Furthermore, in contrast to other opportunistic infection, relapse can occur even at CD4 cell counts above 200 cells/mL." (PMID 23320211, 2012). "Despite the potency of HAART, it has been observed that a significant proportion of patients – despite an adequate virological response – do not achieve CD4 cell recovery above critical thresholds associated with opportunistic infections." (PMID 22348047, 2012).
Opportunistic infection (continued). "Immediate access to CD4 results may also enable more rapid initiation of prophylactic treatment for opportunistic infections as well as chemotherapy for prevention of mother-to-child transmission at sites where CD4 levels define the prophylactic drug regimen." (PMID 22912668, 2012). "As the initial clinics were located at the larger hospitals this preference may be related to the perceived level of available care (availability of CD4 counts or drugs for opportunistic infection) or the relative anonymity of a larger clinic." (PMID 23153311, 2012). "The CD4 t-cell count, the presence of opportunistic infections and use of ART potentially modify the course and the clinical and radiological features of pulmonary TB, and could be associated with diagnostic and treatment delay of TB." (PMID 22958583, 2012). "Therefore, it is important to assess the treatment rates in cases with CD4 of 200–350 cell/μL to ensure treatment coverage and care among these people in order to reduce opportunistic infections in severely immunocompromised patients." (PMID 22536498, 2012). "So early initiation of ART while CD4 counts are higher and opportunistic infections limited, provision of nutritional support and strengthening the food by prescription initiative, and counseling of patients for early presentation during testing for HIV is recommended." (PMID 22606951, 2012). "Non-TB opportunistic infections (p = 0.04) and absolute CD4 count (p = 0.05) were also significantly associated with death." (PMID 21829487, 2011). "While the pathogenesis of secondary complications, such as opportunistic infections and skin tumours, is directly correlated with a decline in the CD4+ T cell count, the origin of the certain manifestations primarily associated with the retroviral infection itself still remains under investigation." (PMID 21261982, 2011). "Other studies have not evaluated the diagnosis of severe sepsis or septic shock as an independent variable on survival analysis, whereas they gave greater emphasis to the presence of opportunistic infections or immunosuppression surrogates (CD4 cell count or viral load)." (PMID 20698966, 2010). "Reduction opportunistic infections, stabilization or increase body weight, CD4 count, thymulin." (PMID 22254046, 2010). "Furthermore, CD4 T cell level determines when to start or stop prophylactic drugs for opportunistic infections." (PMID 19144106, 2009). "It follows that, since CD4+ T cells lymphopenia is not considered to be an univocal marker of risk for opportunistic infections, it is likely that various qualitative parameters of immune response play important roles." (PMID 18974880, 2008). "The proportion of tissue macrophages harbouring HIV-1 may be as high as 50% and they become a major source of virus during opportunistic infection or when CD4+ T cells are depleted." (PMID 18241354, 2008). "While previous studies and ours have identified CD4 cell counts, opportunistic infections, sex, age, nutritional status and financial constraints as being associated with mortality in Africa, other factors such as immune activation have not been studied much in this region." (PMID 19014537, 2008). "Opportunistic infections may also occur before adequate immune-reconstitution can occur when HAART is commenced when the patient has a very low CD4 count." (PMID 15538953, 2004). "Consequently, the number of regenerating CD4+ Tcm cells progressively decreases with the duration of infection, leading to an imbalance in homeostasis and impaired immune function, which can result in opportunistic infections." (PMID 40061947, 2025). "Predominance of CD4+ T lymphocytes in bronchoalveolar lavage fluid indicates a helper T-cell-driven immune response, as seen in granulomatous diseases, such as sarcoidosis, autoimmune and opportunistic infections, or in chronic stages of certain interstitial lung diseases." (PMID 41018418, 2025).
Opportunistic infection (continued). "Additionally, asymptomatic patients, those without opportunistic infections, and those with CD4 T-cell count > 200 cells/mm3 were not at risk for sarcopenia." (PMID 39752996, 2025). "A possible reason might be that low CD4/ immunodeficiency results in serious life-threatening opportunistic infections of the CNS, RS, and GI, as well as others which in turn increases the risk of death in the early stages of treatment before responding to initiated ART." (PMID 38689230, 2024). "This might be because patients with low CD4 lymphocyte counts are more prone to acquiring opportunistic infections which might necessitate the consumption of different drugs leading to subclinical liver damage and thereby increased susceptibility for liver enzyme elevations while taking HAART33." (PMID 38605149, 2024). "However, the PHIV and BHIV groups had similar rates of baseline CD4+ cell count < 200 mm3 (22% vs. 16%, p = 0.348), opportunistic infections before pregnancy (22% vs. 19.5%, p = 0.712) and throughout gestation (9.3% vs. 3.0%, p = 0.124), and clinical hospital admissions (19.5% vs. 16%, p = 0.603)." (PMID 36870111, 2023). "This could be due to the fact that index cases who were at WHO stage III or IV had severe opportunistic infections that exposed the index case to decreased their CD4 levels and increased the viral load levels resulting in high viral transmission to spousal partners." (PMID 36780456, 2023). "Combined with alterations in CD4 cell counts and previous literature reports, we hypothesized that a decrease in CD4 cell counts leads to opportunistic infections of microorganisms colonized in the pancreas, which damage the pancreas or other organs and cause asymptomatic increases in serum amylase." (PMID 36637942, 2023). "While concurrent opportunistic infection remains a leading cause of death in HIV-infected patients, it’s crucial to emphasize that effective antiretroviral therapy can significantly reduce the risk of opportunistic infections by boosting CD4+ T lymphocyte counts and restoring immune function." (PMID 38126075, 2023). "Furthermore, opportunistic infections occurred when CD4 levels were less than 200 cells/mm3." (PMID 37723415, 2023). "This is in line with the SMART and TEMPRANO studies, in which they have shown that starting ART early, regardless of CD4+ T cell count, can lead to improved health outcomes, including a decreased risk of opportunistic infections and, to some extent, a reduction in overall mortality." (PMID 38201498, 2023). "A potential explanation for the very low number of opportunistic infections may be that study patients with low CD4+-T-cell-counts (<200/μl) consequently received anti-zoster and anti-PcP prophylaxis according to guidelines, supporting the strategy of CD4+-T-cell guided prophylaxis." (PMID 37152008, 2023). "Opportunistic infections could lead to depletion of CD4 cells and result in ART treatment failure." (PMID 36408009, 2022). "Moreover, it could help clinicians identify those patients at risk of maintaining low CD4 cell counts and CD4:CD8 ratios and extend the supervision over them in terms of the progression of HIV infection and development of opportunistic infections." (PMID 36298842, 2022). "Second, according to the fact that PLWH with low CD4+ T cell count are more susceptible to opportunistic infection, we could not distinguish the effects of HIV itself or opportunistic pathogens responsible for our findings." (PMID 35967422, 2022). "A recent study found a decrease in the frequency of pre-ART CD4 count measurements after Treat All policy adoption, especially in low/middle income countries, and suggested more research is needed to understand its effect on opportunistic infection prophylaxis management." (PMID 35602655, 2022).